Y_RNA (Y RNA )
Gene: Miscellaneous RNA gene on chromosome 6 (20,500,175 to 20,500,276, forward strand). Ensembl gene ENSG00000201683.
Homologues: Orthologues: macaque Y_RNA (93% identical). Paralogues in human: Y_RNA (90% identical), Y_RNA (88% identical), RNY3 (87% identical), Y_RNA (87% identical), RNY3P1 (86% identical), Y_RNA (86% identical), Y_RNA (85% identical), Y_RNA (84% identical), RNY3P13 (83% identical), RNY3P14 (83% identical), RNY3P7 (83% identical), Y_RNA (83% identical), and 95 more.